SMAD2 (SMAD family member 2)
Diseases named in the same sentence as SMAD2 in open-access papers (continued):
Sharing a sentence is not in itself a finding about the gene and the disease.
ocular hypertension (2 papers, 2020 to 2022). Abnormally high intraocular pressure. "Given the relevance of Smad-dependent TGFβ2 pathways in ocular hypertension and glaucoma, we performed Western blotting to investigate the expression of total and phosphorylated Smad2 and Smad3 molecules." (PMID 32973273, 2020).
osteoradionecrosis (2 papers, 2011 to 2019). Necrosis of bone following radiation injury. "This is consistent with previous immunohistochemistry studies of the TGF-β1 signaling molecule in BRONJ patients showing significantly reduced TGF-β1 and Smad-2/3 in BRONJ patients compared to osteoradionecrosis patients." (PMID 31747953, 2019). "Osteoradionecrosis-affected tissues showed upregulation of TGFβ1 and Smad-2/3 expression and suppression of Smad-7; this was the opposite of findings in BRONJ-affected tissues." (PMID 21726429, 2011). "In the osteoradionecrosis-related group, the labeling index indicated significantly increased cellular Smad-2/3 expression (p < 0.043)." (PMID 21726429, 2011). "In osteoradionecrosis-related mucoperiosteal tissues, increased TGFβ1 and Smad-2/3, together with radiation-induced Galectin-3 were associated with perpetuation of fibrotic soft tissue remodeling and inhibition of re-epithelization {Cao, 2002 #4522}." (PMID 21726429, 2011). "Smad-2/3 expression was observed in the samples of healthy jaw mucoperiosteal tissue, in BRONJ tissues, and in osteoradionecrosis-adjacent soft tissues." (PMID 21726429, 2011). "TGFβ1 and Smad-2/3 were significantly decreased (p < 0.032 and p(0.028, respectively) in the BRONJ samples and significantly increased (p < 0.04 and p <0.043, respectively) in the osteoradionecrosis samples compared to normal tissue." (PMID 21726429, 2011). "In osteoradionecrosis-related mucoperiosteal tissues, the overexpression of TGFβ1 causes an arrest of the EMT process in activated myofibroblasts; conversely, in BRONJ, the lack of TGFβ1 and Smad-2/3 activity attenuated the stimulation of EMT {Schultze-Mosgau, 2004 #2678}." (PMID 21726429, 2011).
pancreatitis (2 papers, 2024). Inflammation of the pancreas. "We previously showed that phopho-SMAD2/3 co-stain with acinar marker Amylase (AMY2) in human pancreatitis tissue, suggesting the activation of the TGFβ pathway in ADM." (PMID 38247878, 2024). "Indeed, CXCR4 inhibition attenuated the phosphorylation of Smad2/3 during pancreatitis." (PMID 38769308, 2024).
papilloma (2 papers, 2012 to 2016). A benign epithelial neoplasm that projects above the surrounding epithelial surface and consists of villous or arborescent outgrowths of fibrovascular stroma. "Deletion of Smad2 in papillomas or SCC or conditional overexpression of Smad2 would help resolve these issues." (PMID 23326666, 2012). "Additionally, the finding that Smad2 phosphorylation levels were similar between CD109+/+ and CD109−/− papillomas could result from the lower amount of stroma found in papillomas compared with in normal skin." (PMID 27756876, 2016). "In two chemical carcinogenesis studies using Smad3+/− and Smad3−/− mice, it was found that in contrast to Smad2 deletion, Smad3+/− mice developed fewer tumors compared to wild-type controls; Smad3−/− mice also developed fewer papillomas than wildtype controls and did not progress to SCC." (PMID 23326666, 2012). "The results show that there were no apparent changes in the levels of TGF-β1 expression or Smad2 phosphorylation between CD109+/+ and CD109−/− papillomas." (PMID 27756876, 2016).
periodontitis (2 papers, 2019 to 2020). An acute or chronic inflammatory process that affects the tissues that surround and support the teeth. "It has been shown that proinflammatory cytokines in periodontitis suppress the TGF-β-mediated expression of NGF by downregulating TGF-β-induced Smad2/3 and p38 MAPK signaling." (PMID 32411181, 2020).
polycystic ovarian syndrome (2 papers, 2024 to 2025). "In the endometrium of women with polycystic ovary syndrome (PCOS), too little GPx4 leads to a TGF-β1/SMAD2/3-driven buildup of extracellular matrix and fibrosis." (PMID 41009046, 2025).
pterygium (2 papers, 2023). A wedge-shaped fibrovascular lesion arising from the bulbar conjunctiva and extending to the cornea. "Knockdown of SPARC attenuates the fibrotic effect induced by TGF-β1 at least in part, by inactivating the SMAD2/3 pathway in human pterygium fibroblasts." (PMID 37569556, 2023). "The canonical Smad2/3 signaling pathway has also been implicated in ECM deposition and myofibroblast activation in pterygium." (PMID 37866886, 2023).
rectal cancer (2 papers, 2008 to 2019). A primary or metastatic malignant neoplasm that affects the rectum. "On basis of integrative analysis this study identified one well known CRC gene (SMAD2) and several other genes (EFNA1, BOP1, TGIF2 and STMN3) that possibly could be used for rectal cancer characterization." (PMID 18959792, 2008). "We identified one well known CRC gene (SMAD2) and several other genes (EFNA1, BOP1, TGIF2 and STMN3) that possibly could be used for rectal cancer characterization." (PMID 18959792, 2008).
ulcer (2 papers, 2017). "The levels of mRNAs encoding TGF-βRI, TGF-βRII, TGF-βRIII, and SMAD2, TGF-β signaling pathway components, were significantly lower in the skin around magnet-implanted ulcers than in the skin around simple defects." (PMID 28687753, 2017). "We showed that epidermal hyperproliferation and TGF-βRI, TGF-βRII, TGF-βRIII, and SMAD2 expression down-regulation were detected in magnet-implanted ulcers." (PMID 28687753, 2017). "For TGF-βR I, SMAD2, and TGFβ-1, 4 of 6 patients showed the same expression patterns; mRNA expression of TGF-βR I and SMAD2 was lower in skin around ulcers than in normal skin, while the expression of TGFβ-1 expression was higher." (PMID 28687753, 2017).
uremia (2 papers, 2013 to 2023). A clinical syndrome associated with the retention of renal waste products or uremic toxins in the blood. "Smad2 and Smad4, TGFBR2 and other members of the TGF-beta and BMP pathways, among the most highly dysregulated probe sets in uremia, may reflect altered bone metabolism." (PMID 23809614, 2013).
urothelial bladder cancer (2 papers, 2019 to 2021). "We evaluated the association of TGF-β1, Smad2, and Smad4, the key components of canonical TGFβ pathway, with clinicopathologic characteristics of urothelial bladder cancer, and assessed their prognostic value in prediction of patients’ outcome." (PMID 31238579, 2019). "Materials and Methods: Immunohistochemical analysis of TGF-β1, Smad2, and Smad4 expression was performed on 404 urothelial bladder cancer samples, incorporated in tissue microarrays." (PMID 31238579, 2019).
urothelial carcinoma (2 papers, 2018 to 2019). A malignant neoplasm derived from the transitional epithelium of the urinary tract (urinary bladder, ureter, urethra, or renal pelvis). "Another study suggested that the highest levels of phosphorylated Smad2 were present in high-grade urothelial carcinoma and were associated with increased recurrence rate." (PMID 31238579, 2019). "The expression levels of GP73, TGF‐β1 and Smad2 in HG urothelial carcinomas were significantly higher than those in LMP papillary urothelial cancers and LG urothelial carcinomas (all P < 0.05)." (PMID 29349903, 2018).
Uterine tumor (2 papers, 2023). "Mice with conditional deletion of SMAD2/3 in the uterine epithelium using Lactoferrin-iCre develop endometrial hyperplasia at 12-weeks and metastatic uterine tumors by 9-months of age." (PMID 36906706, 2023). "Upon gross examination, Smad2/3 cKO mice developed bulky uterine tumors with lung nodules." (PMID 36906706, 2023). "We profiled the data from uterine tumors deposited to the cBioPortal of Cancer Genomics for mutations of the TGFβ signaling pathway and identified several mutations in TGFβ-related receptors (TGFBR1, TGFBR2, ACVR1B, ACVR1C, ACVR2A, ACVR2B) and transcription factors (SMAD2, SMAD3, SMAD4)." (PMID 36906706, 2023).
vitamin D deficiency (2 papers, 2019 to 2023). A nutritional condition produced by a deficiency of VITAMIN D in the diet, insufficient production of vitamin D in the skin, inadequate absorption of vitamin D from the diet, or abnormal conversion of vitamin D to its bioactive metabolites. "In the present study, we showed that vitamin D deficiency aggravated BLM-induced TGF-β/Smad2/3 activation and EMT in the lungs." (PMID 31775746, 2019).
abortion (1 paper, 2017). the ending of pregnancy by removing a fetus or embryo before it can survive outside the uterus. "Collectively, the findings suggested that ESA restricted Foxp3 expression by inhibiting TGFßRII/Smad2/Smad3/Smad4 signalling, ultimately resulting in abortion." (PMID 28300338, 2017).
acute kidney injury (1 paper, 2016). Sudden and sustained deterioration of the kidney function characterized by decreased glomerular filtration rate, increased serum creatinine or oliguria. "The early inhibition of p-Smad2/3 signaling pathway improved impairment of renal function in AA-induced acute kidney injury in rats." (PMID 27379382, 2016).
acute pancreatitis (1 paper, 2014). An acute inflammatory process that leads to necrosis of the pancreatic parenchyma. "In order to study the level of active TGF-β signaling during acute pancreatitis-associated acute lung injury, the activation and subcellular distribution of phosphorylated Smad2 (P-Smad2) were evaluated in lung sections." (PMID 24688224, 2014). "Inhibitory Smad7 expression was transiently increased at 9 h in acute pancreatitis, but reduced later at 24 h, with a concomitant increased nuclear translocation of phosphorylated Smad2." (PMID 24688224, 2014). "However, increased TGF-β signaling via the Smad2 pathway was observed first after 24 h following acute pancreatitis induction." (PMID 24688224, 2014). "However, neither immunostainings nor Western blot analyses showed a significant modulation of the Smad2–4 protein levels in the lungs following 9 or 24 h acute pancreatitis induction compared to sham controls." (PMID 24688224, 2014). "Smad2 was detected at moderate levels in bronchial epithelium, infiltrating cells, and fibroblasts, while low levels were observed in alveoli and vascular endothelial cells in both sham controls and 9 h after acute pancreatitis induction." (PMID 24688224, 2014).
age-related macular degeneration (1 paper, 2024). Age-related loss of vision in the central portion of the retina (macula), secondary to retinal degeneration. "A study has found that in the context of neovascular age-related macular degeneration (AMD), TGF-β2 plays a prominent role by inducing pericyte–myofibroblast transition (PMT) via the Smad2/3 and Akt/mTOR pathways." (PMID 38662949, 2024).
androgen excess (1 paper, 2025). "The Inhba/Smad2/E2f4 axis contributes to thecal cell hyperplasia and androgen excess in PCOS, and may serve as a mechanistic entry point for further investigation into the regulation of TCs proliferation in this disorder." (PMID 40831751, 2025).
B-cell lymphoma (1 paper, 2010). "Moreover, we detected that activin A and B exerted limited anti-proliferative effects on the B-cell lymphoma cell lines, even though clear Smad2 signalling was observed in the TGF-β-sensitive cell lines upon activin A stimulation." (PMID 21092277, 2010).
Barrett adenocarcinoma (1 paper, 2017). An adenocarcinoma arising from Barrett metaplastic epithelium in the esophagus. "Our findings are consistent with previous findings that BMP7 is shown to induce phosphorylation of Smad2/3 in Barrett’s adenocarcinoma cells and that BMP7 stimulates Smad3 target CAGA box promoter activity to a similar extent to that induced by TGF-β in a mammary epithelial cell line." (PMID 27696331, 2017). "In Barrett’s adenocarcinoma cells, Smad2/3 is phosphorylated in the presence of BMP7 and absence of TGF-β, but phosphorylation is inhibited with increasing concentrations of TGF-β." (PMID 27696331, 2017).
Barrett esophagus (1 paper, 2023). Esophageal lesion lined with columnar metaplastic epithelium which is flat or villiform. "For SMAD4, about 70% of esophageal adenocarcinoma (EAC) associated with Barrett’s esophagus (BE) revealed loss of heterozygosity in a region involving SMAD2 and SMAD4 on chromosome 18q." (PMID 37892233, 2023).
bile duct cancer (1 paper, 2022). "Studies have found that LNC-LFAR1 expression inhibition can inhibit bile duct cancer cell proliferation, migration, and invasion, and reduce the expression of Vimentin, Tgf-β1, Smad2, and Smad4." (PMID 35456382, 2022).
bone metabolism disorders (1 paper, 2025). "Additionally, it can stimulate osteoclast differentiation and bone resorption capacity by facilitating Smad2-dependent NFATc1 nuclear translocation and PI3K/AKT/AP-1-mediated pro-inflammatory factor expression pathways, thereby contributing to bone metabolism disorders." (PMID 40136413, 2025).
brain hemorrhage (1 paper, 2025). "Neither Smad2/3fl/fl;Cx3cr1Cre or Tgfb1fl/fl;Cx3cr1Cre mutants showed evidence of neonatal brain hemorrhage." (PMID 40121230, 2025).
Cachexia (1 paper, 2020). Severe weight loss, wasting of muscle, loss of appetite, and general debility related to a chronic disease. "SMAD7 prevents SMAD2/3 phosphorylation, promotes ActRIIB degradation, and was observed to increase muscle mass in healthy mice and attenuate wasting in models of cachexia." (PMID 33250771, 2020).
cartilage tumours (1 paper, 2017). "A high ratio of p-SMAD3 (or p-SMAD2)/PEG10 may be a determinant for cartilage tumours to gain malignancy." (PMID 29044189, 2017).
chronic asthma (1 paper, 2024). An asthma that is characterized by the development of persistent airway inflammation and recurrent attacks of breathlessness and wheezing, which vary in severity and frequency. "In another study of a chronic asthma rat model treated with resveratrol, the phosphorylated SMAD2 and SMAD4 levels were reported to be decreased, but no change was observed in SMAD7 protein expression." (PMID 39055873, 2024).
Chronic colitis (1 paper, 2021). A chronic inflammatory disease of the large intestine (colon, cecum and rectum). "As the main profibrotic transcription factors, SMAD2 and SMAD3 were activated in DSS-induced chronic colitis, and the increased phosphorylation levels of SMAD2 and SMAD3 were reversed by ME treatment." (PMID 34456904, 2021).
chronic Hepatitis C (1 paper, 2016). "In patients with chronic Hepatitis C and advanced fibrosis, upregulation of TGF-β2 correlated well with Smad2 expression." (PMID 26799667, 2016).
chronic lymphocytic leukemia (1 paper, 2020). "CD20, which is regulated by the epigenetic markers NFκB and SMAD2/3, is targeted in chronic lymphocytic leukemia and follicular lymphoma." (PMID 33203436, 2020).
chronic rhinosinusitis (1 paper, 2019). Chronic form of sinusitis. "HSP47 expression is involved in TGF-β1-induced myofibroblast differentiation and ECM production through the Smad2/3 signaling pathway, which might contribute to tissue remodeling in chronic rhinosinusitis." (PMID 31664133, 2019).
clear cell carcinoma (1 paper, 2019).
cognitive decline (1 paper, 2021). "In AD, SMAD2 is also a part of the TGFβ/SMAD2/STAT3 signaling pathway which is activated by APOE, the important risk factor for AD, and increases the amyloidogenic processing of APP leading to Aβ formation and contributes to cognitive decline." (PMID 34502116, 2021).
congenital contractural arachnodactyly (1 paper, 2024). Congenital contractural arachnodactyly (CCA, Beals syndrome) is a connective tissue disorder characterized by multiple flexion contractures, arachnodactyly, severe kyphoscoliosis, abnormal pinnae and muscular hypoplasia. "Genetic variants in genes including TGFBR1, TGFBR2, TGFB2, TGFB3, SMAD2, and SMAD3 result in Loeys–Dietz syndrome and are reported to cause Marfan-like phenotypes and variants in FBN2 and COL3A1 result in congenital contractural arachnodactyly and Ehlers–Danlos syndrome type IV." (PMID 38791509, 2024).
corneal infection (1 paper, 2008). A viral or bacterial infectious process affecting the cornea. "The present study was undertaken to investigate whether transforming growth factor-β (TGF-β) isoforms (TGF-β1, TGF-β2, and TGF-β3) and SMADs (SMAD2 and SMAD3) are involved in herpes simplex virus type 1 (HSV-1) corneal infection." (PMID 18776948, 2008).
dental disorders (1 paper, 2024). "In CRSsNP, Smad2 positively correlated with toothache, likely due to the close proximity of sinus cavities to the roots of the teeth, where both sinus inflammation and dental disorders may interact." (PMID 39338148, 2024).
endometrial disorder (1 paper, 2023). A non-neoplastic or neoplastic disorder that affects the endometrium. "Smad1/5 cKO mice showed endometrial receptivity defects and perturbed embryo implantation, and Smad2/3 cKO mice showed endometrial disorders, sterility, and uterine cancer." (PMID 37947633, 2023).
endometrial tumors (1 paper, 2023). "Given the TGFβ signaling pathway alterations found in human endometrial tumors, we generated mice with epithelial-specific inactivation of Smad225 and Smad315 using Ltf-cre26 (“Smad2/3 cKO” mice) to investigate the in vivo roles of SMAD2 and SMAD3 signaling in the luminal uterine epithelium." (PMID 36906706, 2023).
fasciolosis (1 paper, 2016). "SMAD7 is involved in a negative feedback loop which can suppress the fibrogenic progress mediated by SMAD2/3/4 signaling, indicating that SMAD7 may play a role in controlling fibrosis during the early stage of ovine fasciolosis." (PMID 27661612, 2016).
fibrosarcoma (1 paper, 2019). A malignant mesenchymal fibroblastic neoplasm affecting the soft tissue and bone. "The inhibition of syndecan-2 has also been reported to abolish TGF-β-dependent adhesion with decreased Smad2 activation in fibrosarcoma cells." (PMID 31600983, 2019).
Follicular Cyst (1 paper, 2023). Cyst due to the occlusion of the duct of a follicle or small gland. "FGF7 regulated the PPAR signaling pathway (FABP5 and SCD) and the MAPK signaling pathway (FGF1, FGFR2, IL1A, TGFB1, and CSF1) and pathways in cancer (IL7, CD44, SMAD2, and MMP2) may be involved in the formation of follicular cysts." (PMID 38274662, 2023).
germ cell tumor (1 paper, 2023). A benign or malignant, gonadal or extragonadal neoplasm that originates from germ cells. "The association among failure to downregulate pluripotency genes, the elevation of Nodal/Smad2 signaling, and failure to undergo cell cycle arrest has been reported by multiple investigators studying Dnd mutants, and other models of germ cell tumor development." (PMID 37180974, 2023).
Glucose intolerance (1 paper, 2021). Glucose intolerance (GI) can be defined as dysglycemia that comprises both prediabetes and diabetes. "In vivo zebrafish and mouse models exhibited glucose intolerance, decreased peak GSIS, decreased expression of β-cell identity markers, increased insulin and glucagon co-staining cells, and reduced Tgfb2 and Smad2 expression." (PMID 34246804, 2021).
HCMV infection (1 paper, 2010). "Immunoblotting for phosphorylated SMAD2 (p-SMAD2) in nuclear extracts revealed the presence of p-SMAD2 in nuclei of raTGF-β1 treated cells, both in the presence and absence of HCMV infection, whereas cells that were not treated with raTGF-β1 did not contain nuclear p-SMAD2." (PMID 21079788, 2010).
Hepatitis B (1 paper, 2022). "It is mostly concerned with Hepatitis B, cancer pathways, the IL pathway, the AP1 signaling pathway, the HIF-1 signaling system, the VEGFR1 pathway, prion disorders, endocrine resistance, the Myc pathway, the SMAD2 pathway, the SHP2 pathway, the FRA pathway, and so on." (PMID 35170400, 2022).